RN7SL542P (RNA, 7SL, cytoplasmic 542, pseudogene)
Gene: Miscellaneous RNA gene on chromosome 7 (21,215,537 to 21,215,830, reverse strand). Ensembl gene ENSG00000243633.
Homologues: Orthologues: chimpanzee Metazoa_SRP (99% identical), macaque Metazoa_SRP (91% identical), guinea pig Metazoa_SRP (65% identical). Paralogues in human: RN7SL2 (79% identical), RN7SL1 (79% identical), RN7SL3 (78% identical), RN7SL732P (78% identical), RN7SL126P (78% identical), RN7SL597P (77% identical), RN7SL398P (77% identical), RN7SL804P (77% identical), RN7SL296P (77% identical), RN7SL709P (77% identical), RN7SL122P (76% identical), RN7SL650P (76% identical), and 706 more.